IL4 (interleukin 4)
Diseases named in the same sentence as IL4 in open-access papers (continued):
Sharing a sentence is not in itself a finding about the gene and the disease.
asthma (continued). "The metabolism of arachidonic acid can produce cysteinyl leukotrienes, which is overexpressed in asthma patients and has recently been linked to the production of IL-4, IL-5, and IL-13 by binding ILC2 and Th2 cells." (PMID 37680636, 2023). "Prosekova E.V., Dolgopolov M.S., Sabynych V.A. Gene polymorphism,spontaneous and induced production of interleukin 4 andinterferon gamma by peripheral blood cells in children with asthma.Meditsinskoye Obozreniye = Russian Medical Review." (PMID 37465198, 2023). "Zhang S., Li Y., Liu Y. Interleukin-4 -589C/T polymorphism is associatedwith increased pediatric asthma risk: a meta-analysis.Inflammation." (PMID 37465198, 2023). "Activation of the IL-4 signaling pathway in B cells is known to increase IgE, whose overproduction has been a longstanding hallmark of atopic diseases such as asthma." (PMID 37860183, 2023). "This study showed that Cd4-Cre::Acc1fl/fl mice exhibited attenuated AHR and airway inflammation in OVA- and HDM-induced asthma models due to the enhanced apoptosis and loss of Gata3, Il4, and Il13 expression in lung iNKT cells." (PMID 37917548, 2023). "CRSwNP and asthma share similar pathophysiology and are associated with eosinophilic infiltration and Th2 cytokines such as interleukin-4, interleukin-5, and interleukin-13 (IL-4, IL-5, and IL-13) as well as high levels of local immunoglobulin-E (IgE)." (PMID 37674852, 2023). "In the asthma children group,an increased incidence rate of the TC and TT genotypes ofthe IL4 (C-590T) polymorphism (rs2243250) compared tohealthy ones was shown." (PMID 37465198, 2023). "Nie W., Zhu Z., Pan X., Xiu Q. The interleukin-4 − 589C/T polymorphismand the risk of asthma: A meta-analysis including 7345cases and 7819 controls." (PMID 37465198, 2023). "Single-positive IL-4+ T-cells were more frequent in less severe asthma indicating a pathogenic role for IL-4 high cells." (PMID 37199256, 2023). "Asthma is a complex genetic disorder that has been linked to polymorphisms in the IL-4 gene promoter and proteins involved in IL-4 signaling." (PMID 37765323, 2023). "Both activated Th2 cells and ILC2s produce large amounts of the type-2 cytokines IL-4, IL-5, IL-9, and IL-13, which in turn trigger hallmark asthma symptoms." (PMID 37612281, 2023). "Alongside the canonical cytokines IL-4, IL-5, and IL-13, it is also clear that human Th2 cells can take on characteristics normally associated with other Th subsets in asthma." (PMID 37163370, 2023). "Eosinophils release granules containing IL-4 and IL-10 that further enhance type 2 immune responses commonly associated with asthma." (PMID 37445635, 2023). "Classically, this form of asthma is associated with an increase in serum immunoglobulin E (IgE) antibodies and eosinophilia, as well as the presence of interleukin 4 (IL-4)–, IL-5-, and IL-13-producing cells in bronchoalveolar lavage (BAL)." (PMID 36089628, 2023). "Bhlhe41/Dec2-deficient mice lack the expression of interleukin 4 (IL-4), IL-5, IL-13, and IL-17 in vitro and in vivo in an asthma model and in response to a challenge with a parasite antigen." (PMID 37511489, 2023). "Functionally, Th2A cells have increased expression of IL-5 and IL-9 but a similar expression of IL-4 and IL-13 compared with conventional Th2 cells, aligning with the asthma-associated cluster identified transcriptionally." (PMID 37163370, 2023). "Molecular pathophysiology of T2 asthma is fuelled by activated GATA-3+ CRTH2+ ILC2s as well as Th2 cells that produce substantial amounts of the hallmark type 2 cytokines: IL-4, IL-5, and IL-13." (PMID 37199256, 2023). "Inflammatory cytokines such as interleukin (IL)-4, -5, and -13 initiate the immunopathological action of asthma, causing eosinophilic inflammation, the synthesis of immunoglobulin (Ig)E and chemokines, mucus production, and inflammatory cell infiltration." (PMID 37765323, 2023).
asthma (continued). "We identified markers predisposing to the development of different variants of the course of childhood asthma: the CT genotype and T allele of IL4 rs2243250 are associated with asthma (p < 0.05), especially in mild asthma and in controlled asthma." (PMID 37465198, 2023). "Proinflammatory cytokines IL-4 and IL-13 secreted by Th2 are closely associated with mucus secretion, eosinophil activation, and airway remodeling in asthma." (PMID 37873538, 2023). "Liu S., Li T., Liu J. Interleukin-4 rs2243250 polymorphism is associatedwith asthma among Caucasians and related to atopic asthma.Cytokine." (PMID 37465198, 2023). "Another study found that higher levels of parental support were concurrently associated with lower levels of stimulated IL-4 production in a clinical sample of adolescents with asthma." (PMID 34347228, 2023). "IL-5 and IL-4/IL-13 are considered the key drivers of type 2 pathways underlying eosinophilic airway inflammation in asthma." (PMID 37108417, 2023). "A Th1/Th2 imbalance plays an important role in the pathogenesis of asthma and the Th2-associated cytokines interleukin (IL)-4 and -5 are released abnormally to trigger an inflammatory response." (PMID 35040955, 2022). "Respiratory allergic diseases, including asthma, are associated with type 2 cytokines, such as interleukin-4 (IL-4), IL-5, and IL-13, which induce airway eosinophilia, mucus hyperproduction, AHR, and immunoglobulin (Ig)E class switching." (PMID 35911708, 2022). "Interleukin (IL)-4 and IL-13 are critical cytokines in the induction of the pathogenic Th2 responses in AR and asthma." (PMID 35663523, 2022). "Next, Elevated serum total IgE levels, as marker for asthma, was obviously decreased in sTSLP group, as well as levels of Th2-associated cytokines (IL-4, IL-5 and IL-13) in the BALF of mice." (PMID 35351157, 2022). "Studies on the epigenetic regulation in these populations have revealed that both Th2 and Treg cell populations can be influenced in a heritable manner, with epigenetic changes at the IL4 promoter being associated with a predisposition to develop asthma." (PMID 35693821, 2022). "It was reported previously that there is an overlapping between asthma susceptible genes at loci 17q12-21 and genes controlling the expression of IgE, including IL-4 gene." (PMID 36201519, 2022). "It is well known that IL-13 causes an over-reaction in the airways and IL-4 stimulates mucus secretion, which are obvious indicators of asthma." (PMID 35419072, 2022). "This stems from the fact that asthma is associated with enhanced IL-4-associated STAT6 phosphorylation and subsequent production of Th2 cytokines." (PMID 36348405, 2022). "The pro-M(IL-4) effects of SP-A reported here and in contrast with reports that associate SP-A with protection in asthma and fibrosis." (PMID 35444643, 2022). "Th2 cell-derived cytokines including interleukin-4 (IL-4), IL-5, and IL-13 underlie the inappropriate immune response, and lead to anaphylactic diseases such as asthma, chronic rhinitis, atopic dermatitis, and certain types of gut disorders." (PMID 36564797, 2022). "Asthma has long been considered as a Th2-associated inflammatory disease, with IL-4, IL-5, and IL-13 as the key cytokines and eosinophilic infiltrates in the airways." (PMID 35408882, 2022). "Among these cytokines, IL-4 and IL-5 are mainly implicated in cardinal features of asthma, maturation of eosinophils and goblet cell, IgE mediated hypersensitive response, mucus secretion, bronchial constriction, and tissue remodeling." (PMID 38143476, 2022). "Several recent studies have linked the pathogenesis of asthma caused by IgE and IL-4 to a TH17-dependent mechanism." (PMID 36081945, 2022). "For instance, IL-13+2044G/A, IL-4-590C/T polymorphisms are associated with an increased risk of childhood asthma development." (PMID 35812388, 2022).
asthma (continued). "Type 2 airway inflammation induced by antigen-specific immunoglobulin E (IgE), interleukin-4 (IL-4), IL-5, IL-13, and thymic stromal lymphopoietin is associated with increased exacerbations and airway remodeling in patients with asthma." (PMID 35756113, 2022). "Asthma-associated biomarkers include immune cells (T-helper, Th1, Th2), cytokines (IL-4, IL-13), eosinophils, mast cells, and neutrophils that form an inflammatory infiltrate in the lung airways causing adverse symptoms." (PMID 36115955, 2022). "Although IL-4-activated macrophages have recently emerged as important players in homeostatic processes, chronic respiratory diseases such as fibrosis, asthma, and allergy are associated with a dysregulated type 2 response." (PMID 35444643, 2022). "Our findings indicate that IL-4 expression by B cells promotes Th2 responses that underlie allergic diseases such as asthma." (PMID 35359977, 2022). "Another SNP in the promoter region of the IL-4 gene (rs2243250) has been shown to increase the risk of asthma in children and adults." (PMID 36292755, 2022). "Exuberant production of IL‐4, IL‐5, and IL‐13 leads to asthma features with the accumulation of type 2‐associated cells, such as eosinophils, in lung tissue." (PMID 35758054, 2022). "In HBE cells, TNC expression is increased by rhinovirus infection, a risk factor for asthma, and type 2 cytokines including IL-4 and IL-13, critical mediators of asthma development." (PMID 35053372, 2022). "Hoverer, asthma comorbid AR patients showed an increase in the expression of systemic cytokine (IL-4, IL-5, and IL-25) in plasma; this was associated with a lower quality of life than that of patients with asthma." (PMID 35348596, 2022). "According to reports, genetic polymorphisms affecting the IL-4/IL-13 axis were associated with asthma susceptibility and risk association between IL-4 and IL-13 genes polymorphisms and food allergy." (PMID 36364962, 2022). "CD4+CRTH2+CCR6+ cells secrete IL-17, IL-4 and IL-13, leading to the infiltration neutrophils and eosinophils, which is responsible for chronic inflammation associated with asthma." (PMID 34090369, 2021). "The pathogenic mechanisms of AD are similar to asthma, as they are both Th2-driven diseases with the enhancement of IL-4, IL-5, and IL-13 cytokines that can induce eosinophils and IgE recruitment." (PMID 34572281, 2021). "The Fulani group also have a higher prevalence, when compared to neighbouring ethnic groups, of an IL-4 polymorphism associated with allergy and asthma." (PMID 34383742, 2021). "Type 2 (T2)-high asthma is associated with elevated levels of Th2 cytokines such as IL-4, IL-5 and IL-13 whereas T2-low asthma is mainly linked to the activation of Th1 and Th17 cells." (PMID 34777398, 2021). "Several pathophysiological pathways are associated with the development of asthma, including those that mediate the release of cytokines involved in the inflammatory process, in particular IL-4, IL-9, IL-13, and IL-17." (PMID 33577738, 2021). "In asthma pathogenesis, the overexpression of several type 2 inflammatory mediators including IgE, IL-4, IL-5, IL-13, and TSLP has been associated with ASM hyperreactivity, all of which can be targeted by humanized monoclonal antibodies (mAbs)." (PMID 34572466, 2021). "Our previous study showed the association of IL-4, its receptor IL4Rα and IL-13 polymorphisms with asthma in the same pediatric cohort that was analyzed in this study." (PMID 34946286, 2021). "Eosinophilic inflammation is a hallmark of all forms of asthma, and is a consequence of the uncontrolled production of IL-4, IL-13, and IL-5." (PMID 34948449, 2021). "Allergen challenges induce IL-4 release into the peripheral blood, with IL-4 levels exacerbating peribronchial inflammation causing asthma." (PMID 34836513, 2021).
asthma (continued). "Since CP and OA inhibited IL-5 in BALF and Th2 cytokine (IL-5, IL-4, and IL-13) production in spleen cells, we assessed the mRNA expression of asthma-associated cytokines and mediators in the lung tissues of OVA-induced asthmatic mice using qRT-PCR." (PMID 33806085, 2021). "Interleukin (IL)-4/IL-13 pathway genes, including IL-4, IL-13, IL-4 receptor alpha (IL-4Ra), and signal transducer and activator of transcription 6 (STAT6), were frequently linked to serum IgE levels and asthma as they can regulate IL-4 and IL-13 cytokines." (PMID 33810791, 2021). "In murine model of maternal asthma, IL-4 blockade—key Th2 cytokine, decreases the conferring risk in offspring, whereas IFN gamma, known for its anti-allergic function, has the opposite effect." (PMID 33971945, 2021). "Asthma is thought to be a Th2 cell-associated inflammatory disease, and Th2-type cytokines, such as IL-4 and IL-13, which can activate B cells to produce allergen-specific IgE, are considered to drive disease pathology in patients." (PMID 34421593, 2021). "IL-4 plays another role in asthma through the induction of mucin gene expression, causing the hypersecretion of mucus from goblet cells within the airways." (PMID 34948449, 2021). "Asthma is caused by hyperreactivity to benign antigens, with humoral immunity orchestrated by interleukin-4 (IL-4) and IL-13 being the key etiological factor." (PMID 33976140, 2021). "One of the underlying causes of asthma and inflammatory responses of respiratory infection are induced by Th-2-type cytokines such as IL-4 and IL-13." (PMID 34226412, 2021). "Asthma is associated with hypomethylation of IL-4, RUNX3, and TIGIT in blood, at genetic loci 5q31.1, 1p36.11, and 3q13.31, respectively." (PMID 34566492, 2021). "For example, the cytokine IL-4 has been found to induce secretion of IgE which is linked to increased symptoms of asthma." (PMID 34712855, 2021). "In vivo studies in murine models of asthma revealed that both anti-IL-4 antibodies and soluble IL-4 receptors can block the downstream events associated with asthma." (PMID 34572281, 2021). "While only preliminary studies, these trials further solidify that IL-4- and IL-13-related inflammation are directly linked to asthma, and can be a target for therapeutic intervention." (PMID 34948449, 2021). "To resolve the incongruent outcomes yielded from different single studies, we conducted the most up-to-date meta-analysis of IL4 gene −589C/T (rs2243250) polymorphism and susceptibility to asthma." (PMID 33087044, 2020). "Subgroup analysis by continent revealed a significant association between IL-4 C33T polymorphism and asthma risk in the European population." (PMID 33228581, 2020). "Previously, three meta-analysis studies have attempted to disclose the association of IL4 gene −589C/T SNP with the risk of asthma." (PMID 33087044, 2020). "In the overall study populations, a significant positive association was detected under all genotype models and announced the IL-4 C33T polymorphism as a potential risk factor in the pathogenesis of asthma." (PMID 33228581, 2020). "Hyper-methylation of IL-4, IL-5, and eosinophil peroxidase were reported in two cohorts of children with asthma and were linked to impaired IP3-mTOR signaling." (PMID 31979396, 2020). "Among the SNPs in the IL4 gene, the -589C/T (rs2243250) polymorphism has been widely investigated in susceptibility to asthma." (PMID 33087044, 2020). "The subgroup analysis by age indicated that IL4 gene -589C/T polymorphism was significantly associated with asthma risk in both pediatrics and adults." (PMID 33087044, 2020). "Eosinophilia during asthma development is associated with pro-inflammatory cytokines such as IL-4, IL-5 and IL-13." (PMID 31991647, 2020). "This study suggests that IL-4 C33T polymorphism potentially acts as a risk factor for asthma in different ethnicities and age groups." (PMID 33228581, 2020).
asthma (continued). "The inflammation caused by asthma is originated from Th2 lymphocytes, which secrete a group of cytokines including IL-5, IL-4, IL-3, IL-13 and GM-CSF." (PMID 32489374, 2020). "Our current meta-analysis composed of 24 publications (28 studies) involving 6587 cases and 8408 controls, we systematically assessed the relationship between IL-4 C33T polymorphism and asthma susceptibility." (PMID 33228581, 2020). "To date, several individual case-control replication studies have attempted to divulge the association of IL4 gene -589C/T polymorphism and risk of asthma." (PMID 33087044, 2020). "During asthma, there is an increase in mitochondrial dysfunction and the hallmark asthma cytokine, IL-4, is associated with increased mitochondrial damage." (PMID 33352732, 2020). "Accordingly, we conducted a meta-analysis to conclude a more exact estimation of the relation between the IL-4 C33T polymorphism and risk of asthma." (PMID 33228581, 2020). "Cumulatively, the result illustrated IL-4 C33T polymorphism as a risk factor in the pathogenesis of asthma." (PMID 33228581, 2020). "At the turn of the millennium genetic polymorphisms of the IL-4 gene in the development and maintenance of asthma have drawn increasing consideration." (PMID 33228581, 2020). "The increased number and activity of mast cells mainly cause asthma, which involves many signaling pathways, in which the role of IL-4/STAT6 pathway in mast high sensitivity has been studied." (PMID 33228696, 2020). "There are several studies in which association between IL-4 C33T polymorphism and asthma risk have been evaluated." (PMID 33228581, 2020). "Conversely, all genotype models were significant in Caucasians and presence of IL4 gene -589C/T SNP increase risk of asthma." (PMID 33087044, 2020). "Eosinophils, sources of IL‐4 and IL‐13, have been implicated in tissue remodeling in other diseases including eosinophilic oesophagitis, asthma, and hypereosinophilic syndrome." (PMID 32567222, 2020). "With taking these factors into account in future studies, it would ultimately lead to our comprehensive and better understanding of the association between the IL-4 C33T polymorphism and asthma susceptibility." (PMID 33228581, 2020). "IL-4 gene is located on long arm of chromosome 5 (5q31), a region that has been associated with asthma or related disorders such as bronchial hyper responsiveness (BHR) and atopy." (PMID 33228581, 2020). "The Th2-type cytokines, IL-4, 5, and 13, which are associated with the promotion of IgE and eosinophilic responses mostly in atopy and asthma, and IL-10, characterized by anti-inflammatory response, were explored in ACO." (PMID 32448302, 2020). "Despite the glucocorticoid therapies have a great effect on maintaining the balance of Th1/Th2 in asthma, more studies have paid attention to various treatments targeting Th2-associated IL-4, IL-5, or IL-13." (PMID 33013382, 2020). "Overall, 55 studies with 9572 cases and 9881 controls included in quantitative analysis of the association between IL-4 gene -589C/T polymorphism and the risk of asthma." (PMID 33087044, 2020). "The results highlighted a predisposing role of IL4 gene -589C/T polymorphism for the asthma risk in pediatrics and adults under all genotype models." (PMID 33087044, 2020). "In the Asian population, there was a significant association between IL-4 C33T polymorphism and the risk of asthma under recessive and allelic models." (PMID 33228581, 2020). "Taken together, this study suggests that IL-4 C33T polymorphism potentially acts as a risk factor for asthma in different ethnicities and age groups." (PMID 33228581, 2020). "All in all, here we carried out the most up-to-date analysis of the IL4 gene 589C/T polymorphism and asthma risk prior to September 2020." (PMID 33087044, 2020).